IL10 (interleukin 10)
Diseases named in the same sentence as IL10 in open-access papers (continued):
Sharing a sentence is not in itself a finding about the gene and the disease.
COVID-19 (continued). "However, COVID-19 individuals also showed increased levels of the anti-inflammatory cytokine IL-10 at baseline (p<0.05) and after spike stimulation (p<0.05); all together suggested that the Th1/Th2 profile is not altered even under the coinfection context." (PMID 40458413, 2025). "High levels of IL-6 and IL-10 could be related to the overactivation of Th2 immune-mediated responses, resulting in disease progression to the critical COVID-19 stage or even death." (PMID 40508859, 2025). "In this single-center cohort of moderate-to-severe COVID-19, we evaluated whether early changes in the inflammatory balance between IL-6 and IL-10 were summarized by the DBS-track short-term clinical trajectory." (PMID 41322840, 2025). "We suggest that both IL-6 and IL-10 might be useful biomarkers to improve diagnosis and severity stratification in COVID-19 patients and possibly tailor treatment accordingly." (PMID 40508859, 2025). "This study highlights the associations of the IL-6 rs1800796 (-572 G/C), IL-10 rs1800871 (-819 C/T), rs1800872 (-592 C/A) and CCL5 rs2107538 polymorphisms with fatal COVID-19 outcomes and elevation of cytokines (CCL-2, IL-6, IL-10 and CXC-L10) plays a crucial role in the pathogenesis of COVID-19." (PMID 40881695, 2025). "Likewise, 61% of COVID-19 patients with elevated proinflammatory cytokines (IL-6 and IL-10) had a fatal outcome." (PMID 40508859, 2025). "Notably, interleukin-6 (IL-6) and tumour necrosis factor were identified as hub cytokines connecting SLE to COVID-19 infection, while IL-6 and interleukin-10 (IL-10) were pivotal in connecting SLE to COVID-19 severity." (PMID 40643149, 2025). "Further analysis showed an overall lower correlation between the cytokines IL-2R, IL-6, IL-7, IL-8, and IL-10 and metabolic phenotype 3 among non-survivors, indicating a lower association of these cytokines with COVID-19-related metabolites." (PMID 41002992, 2025). "Compared to the cured and discharged COVID-19 patients (n = 54), expression levels of miR-155 and IL-6/IL-10 ratio were significantly higher in patients who died (n = 21) (p-values = 0.001), while serum level of IL-10 was significantly lower (p-value < 0.001)." (PMID 41203712, 2025). "However, carriers of the IL-10 (rs1800872, rs1800871) and CCL-5 (rs2107538) gene variants were associated with patients who died from COVID-19." (PMID 40881695, 2025). "The aim of this study was to investigate serum IgE, IgG, and the counts of eosinophils and basophils, as well as the levels of interleukin-10 (IL-10) and interleukin-33 (IL-33), in COVID-19 patients using fresh and frozen serum samples collected during the pandemic." (PMID 41157211, 2025). "In addition to its classical anti-inflammatory effects, there are two proposed mechanisms for the increase of IL-10 in ARDS COVID-19 patients." (PMID 40761632, 2025). "Reverse causality of COVID-19 with 3 suggestively related inflammatory proteins IL-10, IL-18, and PD-L1 showed none to be significant (P > .05)." (PMID 40101060, 2025). "In the literature, the T allele of rs1800872 has been associated with increased serum of IL-10 levels, higher risks of cervical cancer development, and higher frequencies of severe and decreased outcomes in non-vaccinated COVID-19 patients." (PMID 41010422, 2025). "Moreover, the identification of the –1,082 A/G SNP in the IL-10 gene as a potential protective genetic determinant against ARDS severity in COVID-19 underscores the importance of personalized medicine approaches." (PMID 40761632, 2025). "Traditionally recognized for its anti-inflammatory properties, IL-10’s increased presence in severe instances of COVID-19 might reflect the body’s compensatory response to mitigate the disease’s rampant inflammation." (PMID 39203987, 2024). "IL-10 has been hypothesized to play a role in regulating the immune response in COVID-19 patients, while G-CSF has been shown to stimulate the production of neutrophils, which contributes to lung inflammation." (PMID 38793604, 2024).
COVID-19 (continued). "As with IL-6, IL-10 has been proposed as a predictive marker, suggesting that measuring IL-6 and IL-10 levels could be useful in assessing the prognosis of patients with COVID-19." (PMID 38601541, 2024). "Therefore, our study revealed that the expression of cytokines, such as IL-6 and IL-10, which have been consistently verified to be involved in the progression of COVID-19 by other studies, is up-regulated as the disease gradually became more severe." (PMID 38710800, 2024). "After being confirmed that COVID-19 patients have higher levels of Gal-1, Gal-3, and prostaglandin E2 (PGE2) compared to healthy patients, the positive association between Gal-1 and IL-1β, IL-6, IL-10, IL-23, IL-33 was studied and proven." (PMID 38540252, 2024). "Additionally, our study demonstrated that elevated levels of respiratory immune mediators, including IL-10, IL-6, MCP-1, and MCP-3, were significantly associated with COVID-19 severity." (PMID 39633683, 2024). "In addition, an increase in central memory Tregs with elevated expression of CTLA-4 and IL-10 was observed in patients with mild, moderate, and severe COVID-19." (PMID 39519310, 2024). "In our investigation, we discerned that the levels of S1RBD IgG, along with cytokines IL-6, IL-6R, TNF-α, IL-10, and IL-1β, were markedly elevated in the individuals who received two or three doses of the mRNA COVID-19 vaccine compared to those who received a single dose." (PMID 38932387, 2024). "Except for IL-8 decreased in the second trimester after infected with SARS-CoV-2, IL-2, TNF-α, TNF-β, IFN-γ, IL-4, IL-5, IL-6, IL-10, IL-17A, IL-17F, IL-22, IL-1β and IL-12p70 didn't change in the three trimesters between healthy pregnancies and pregnant women with COVID-19." (PMID 39113896, 2024). "Dysregulation of the IL-10-sphingolipid metabolism axis may also contribute to pathology in other clinical conditions such as COVID-19, where aberrant IL-10 production as well as alterations in sphingolipid metabolism and signaling has been reported." (PMID 39132450, 2024). "In COVID-19 patients, abnormal activation of macrophages expressing M1/M2 polarization markers (CD68, CD80, CD163, and CD206) in the lung is associated with the production of cytokines, including IL-6, IL-10, and TNF-α, as indicated by previous studies." (PMID 39100091, 2024). "Furthermore, COVID-19 patients had a higher frequency of the polymorphic A allele of TNF-α, the A allele of IL-8, the G allele of IL-10, and the T allele of CXCR2." (PMID 38544825, 2024). "The utility of compound scores, particularly a weighted sum of IL-6, MCP, CXCL, IL-6, IL10, IL-17A, and IL-1β, were particularly stronger in predicting disease severity, reinforcing the potential of a multifaceted biomarker approach in managing COVID-19." (PMID 39062105, 2024). "However, critical and severe COVID-19 patients present higher IL-6 and IL-10 plasma levels compared to moderate cases of the disease." (PMID 38474248, 2024). "In BAL fluid, only the levels of CCL8, CXCL10, and CCL7 were significantly lower, and the levels of IL-10 were higher, in patients with COVID-19 after they received corticosteroids compared with those who did not receive corticosteroids (q < 0.05, Mann-Whitney)." (PMID 38502186, 2024). "Similarly, IL10 rs1800896 with the genotype A/A, indicative of lower protein expression, was more frequent among COVID-19 patients than healthy controls." (PMID 39518964, 2024). "The role of IL-10 in type-1 and type-2 inflammation, as well as COVID-19, remains to be determined." (PMID 38932242, 2024). "In this study, we screened for c-aAb targeting IFNα, IFNβ, IFNγ, IL-1α, IL-6, IL-10, and GM-CSF in the Surviving Pneumonia Study cohort, comprising 665 patients with CAP caused by COVID-19, influenza virus, bacteria, or unknown pathogen." (PMID 39606243, 2024). "Out of the two children with significantly elevated IL-10 levels, one developed severe COVID-19." (PMID 38355623, 2024).
COVID-19 (continued). "IL-10+ Breg population frequency is diminished in patients with critical and severe COVID-19, and corresponds to a hyperinflammatory response marked by increase in clinical inflammatory parameters including neutrophil/lymphocyte ratio, D-dimer presence etc in patients." (PMID 39346706, 2024). "Of note, decreased lymphocyte subsets and increased cytokines (IL-6, IL-8, IL-10 and IFN-γ) may aid the early identification of patients at risk of severe and critical COVID-19 and provide more definitive and timely approaches for treatment." (PMID 38173531, 2024). "Furthermore, the nuanced role of IL-10 in COVID-19’s immunopathology can be paralleled with findings in other inflammatory conditions, where an elevated NLR, alongside heightened levels of pro-inflammatory cytokines, has been associated with adverse outcomes." (PMID 39203987, 2024). "This study shows albumin, lymphocytes, platelets and ferritin as factors that may correlate with the severity of COVID-19, and with regard to pro-inflammatory cytokines, the authors found IL-6, IL-10, IL-2 and IL-17 to be elevated in severe patients." (PMID 38807995, 2024). "Moreover, age, IL-8, IL-10, CD8+cells and NK cell were independent risk factors for the severity of COVID-19." (PMID 38173531, 2024). "Similarly, IL10 levels show various correlations with altered metabolite levels in infected COVID-19 patients." (PMID 39040605, 2024). "Thus, in children with COVID-19 and appendicitis, an increase in pro-inflammatory cytokines IL-1 and IL-6, as well as anti-inflammatory cytokines IL-4 and IL-10, is observed." (PMID 38397914, 2024). "Increased and prolonged IL-10 in the hyperinflammatory conditions of COVID-19 may be related to excessive stimulation and exhaustion of cytotoxic effector CD8 + T cells." (PMID 39739157, 2024). "The low IFNγ response to SARS-CoV-2 and high levels of immunosuppressive IL-10 in COVID-19 and dengue during the early phase of illness indicate a poor antiviral reaction that could contribute to disease severity." (PMID 39519178, 2024). "The primary objective of this study is to assess the predictive value and diagnostic potential of specific interleukins (IL-10, IL-17A, IL-1β, IL-6), chemokines (CXCL), and monocyte chemoattractant protein (MCP) in predicting severe COVID-19 outcomes and mortality." (PMID 39062105, 2024). "Interestingly, an increased level of the antiinflammatory IL-10 has been reported in severe COVID-19 patients." (PMID 39739157, 2024). "The risk of susceptibility to COVID-19 was significantly associated with TNF-α rs1800629 GA, GA+AA genotypes and the A allele, IL-8 rs4073 TA, AA genotypes and A allele, IL-10 rs1800872 GA and CC genotypes and C allele, and CXCR2 rs2230054 CT and CT+CC genotypes." (PMID 38544825, 2024). "In addition, IL-10, an anti-inflammatory cytokine known for its potent immunosuppressive effects, was dramatically elevated in COVID-19 patients when compared to healthy controls and strikingly higher in deceased COVID-19 patients." (PMID 39345212, 2024). "Similarly, patients with severe COVID-19 were found to have high plasma levels of IL-10, MCP-1, and TNF-α." (PMID 39506759, 2024). "Interestingly, it has been demonstrated that elevated IL-10 levels positively correlate with the severity of COVID-19, especially in patients with diabetes." (PMID 39340009, 2024). "MIS-C may be distinguishable from severe COVID-19 by cytokine profile differences such as increased IL-10 in MIS-C." (PMID 40012912, 2024). "Therefore, the aim of the current study was to investigate the association between the IL-6 rs1800796, IL-10 rs1800896, TNF-α rs1800629, and IFITM3 rs12252 polymorphisms and the presence of post-COVID symptoms in previously hospitalized COVID-19 survivors." (PMID 38400050, 2024).
COVID-19 (continued). "Taken together, our data show that IFN-γ-licensed MSCs are capable of modulating the immune response triggered by the inflammatory milieu produced by lung cells exposed to NS antigens, reducing the levels of critical cytokines in COVID-19, such as IL-10 and IL-6." (PMID 39415027, 2024). "The blend significantly reduced pro-inflammatory cytokines, such as IL-6, while increasing anti-inflammatory IL-10, suggesting that it helps modulate cytokine levels and counteract the hyperactivation caused by SARS-CoV-2, potentially reducing COVID-19 progression and sequelae." (PMID 39599909, 2024). "Interestingly, we found that IL-10, IL-23, and TNF-α were strongly associated with COVID-19 mortality, as demonstrated by ROC curve and multivariate regression analysis." (PMID 37283736, 2023). "There is also a study of the Mexican population, where the effect of IL10 genetic polymorphisms rs1800871 and rs1800872 on the clinical outcomes of COVID-19 has not been confirmed." (PMID 37390087, 2023). "The high expression levels of IL-6, TNF-α, and IL-10 may have led to cytokine storms in the neonates of mothers with COVID-19 because the relationship of those cytokines with the event has already been demonstrated in other studies." (PMID 36979888, 2023). "In particular, PC1 reflected the known hyper-inflammatory phenotype of COVID-19 (with greatest contributions from IL-2, IL-6, IP-10, TNF-α, IL-10, IL-33 and IL-1β) which was independently associated with severe disease, requirement for invasive mechanical ventilation and mortality." (PMID 37063871, 2023). "For instance, the early and dramatic rise in IL-10 after SARS-CoV-2 infection may play a harmful pathological role in the severity of COVID-19." (PMID 37735372, 2023). "Patients with severe COVID-19 have a high level of circulating IL-2, IL-6, IL-7, IL-10, and IFN-γ." (PMID 37654571, 2023). "It has been hypothesized that death from COVID-19 may be associated with immunogenetic markers including IL12B, along with HLA-B, IL6, and IL10." (PMID 36800980, 2023). "In contrast to the present study, a study in Mexico indicated that the IL10 rs1800871 and rs1800872 polymorphisms among 193 COVID-19 patients were not linked to the severity of the disease." (PMID 36882862, 2023). "Considering that immunity and inflammatory responses are closely associated with the clinical manifestations of COVID-19 and outcomes, the levels of peripheral CD3+, CD4+, and CD8+ T cells as well as the levels of TNF-α, IL-6, and IL-10 were also determined in this study." (PMID 38249419, 2023). "A study showed that the IL-6/IL-10 ratio is a more ideal prognosis biomarker for COVID-19." (PMID 36914565, 2023). "Finally, post- COVID-19 presented an increased LPS-stimulated whole- blood IL-10 concentration (p adj <0.01)." (PMID 37753077, 2023). "Moreover, increased serum levels of IL-10 have been observed in patients with critical COVID-19 compared with patients with severe or moderate illness." (PMID 37715121, 2023). "However, in our analyses, only IL-6 and IL-10 were identified as representative of the Th2 profile in newborns of mothers with COVID-19." (PMID 36979888, 2023). "One study reported elevated IL-10 levels in patients with COVID-19 with ARDS; however, whether this serves a protective or harmful role remains unknown." (PMID 36914565, 2023). "Based on the results of the in vivo COVID-19 cytokine storm study, we focused on the IL-1β, IL-2, IL-6, TNFα, IL-4, and IL-10 molecular pathways as the key elements of the inflammatory response in order to identify the molecular mechanisms of peptidergic regulation of the cytokine storm in COVID-19." (PMID 37686182, 2023). "Significant decreases in plasma concentrations of the pro-inflammatory cytokines IL-6, TNF, and IFN-γ, the leukocyte chemoattractants CXCL8, CXCL10, and CCL2, and the anti-inflammatory cytokines IL-10 and IL-1Ra were observed in COVID-19 patients during dexamethasone treatment." (PMID 37614228, 2023).
COVID-19 (continued). "In this study blood levels of sP2X7R measured at the time of diagnosis at hospital admission in a cohort of COVID-19 patients were correlated to (a) several markers of inflammation and tissue damage, (b) sNLRP3, IL-6, IL-10, and IL-1β levels, and most importantly, (c) disease progression." (PMID 37215142, 2023). "First, we studied the profile of different soluble pro-inflammatory cytokines (GM-CSF, TNF-α, IFN-γ, IL-1β, IL-2, IL-6, IL-7, IL-10, IL-17A, IL-21) and chemokines mediating monocyte and neutrophil recruitment (IL8, CCL3), whose exacerbated production is associated with severe COVID-19." (PMID 36675231, 2023). "In addition, the authors suggested that the measurement of IL-6 and IL-10 concentrations should be an option to predict mortality in COVID-19." (PMID 36766961, 2023). "The ROC curve of IL-10 for prognosing COVID-19 was also analyzed." (PMID 37283736, 2023). "Additionally, several studies highlighted that inflammatory cytokines such as IL-6 and IL-10 were present in highest levels in severe COVID-19 (acute) compared to moderate/mild or HC." (PMID 37228606, 2023). "However, T cell responses against all the tested proteins, except ORF3a, showed statistically significantly higher IL-10/IFN-γ ratios in asymptomatic participants from Elgeyo Marakwet compared with ratios in the Singaporean COVID-19 convalescents." (PMID 37219944, 2023). "Several studies confirmed dramatically increment of IL-10 in COVID-19 patients." (PMID 36702907, 2023). "Similarly, increases in IL-10 were significant among patients with COVID-19 and bacterial pneumonia, with the COVID-19 group showing a higher, though not statistically significant, increase." (PMID 38585537, 2023). "In addition, TGFβ1, TGFβ3, IL-10, and IL-6 were prognostic makers for the early phase of COVID-19 severity, consistent with previous reports." (PMID 37569646, 2023). "The pro-inflammatory environment and the triad of high systemic levels of IP-10, IL-10, and IL-6 depicted in severe patients from the first COVID-19 wave from Argentina have been reported in other cohorts, also occurring with a reduced frequency of circulating Treg." (PMID 37809093, 2023). "Furthermore, targeting IL-6 and IL-10 has been proposed for treating ARDS in COVID-19 patients based on its immunoregulatory functions." (PMID 38249419, 2023). "However, even 2–3 months after recovering from COVID-19, alterations in the levels of both pro-inflammatory cytokines, such as IL-1β, IL-6, TNFα, and the anti-inflammatory cytokine IL-10, have been observed in semen." (PMID 37958725, 2023). "In this scenario marine microalgae are emerging as rich sources of a wide range of bioactive metabolites with anti-antioxidant and anti-inflammatory properties that can serve as potential new therapeutic agents to treat or prevent the severe symptoms of COVID-19, possibly by enhancing IL-10 levels." (PMID 37359549, 2023). "This review proposes IL-10 as a new therapeutic strategy for COVID-19 with ARDS." (PMID 36914565, 2023). "In addition, several biomarkers of inflammation were upregulated in COVID-19 patients compared to the disease controls donors, namely IP-10, IL-10, and RAGE." (PMID 36999030, 2023). "A total of 102 intersected gene targets were obtained based on 246 active ingredient-related targets and 4829 COVID-19-related disease targets, which are possible key gene targets of the bitter almond-licorice for the treatment of COVID-19, such as IL10 and IL6." (PMID 38018195, 2023). "In this work we found elevated proinflammatory cytokines IL-6, IL-10, IL-2 and IL-17, and importantly we noted that 12 of 20 COVID-19 severely ill patients and 13 of 20 critically ill patients had lymphopenia (lymphocyte values below 1000/ mL), which coincides with the observations of other authors." (PMID 36835858, 2023).